ALDOA (aldolase, fructose-bisphosphate A)
Diseases named in the same sentence as ALDOA in open-access papers (continued):
Sharing a sentence is not in itself a finding about the gene and the disease.
epilepsy (1 paper, 2023). A brain disorder characterized by episodes of abnormally increased neuronal discharge resulting in transient episodes of sensory or motor neurological dysfunction, or psychic dysfunction. "Validation of epilepsy and stress cardiomyopathy co-expressed genes at the single-cell level revealed that ALDOA, CTSZ, ERBBS, HLA-DMB and other genes were validated as double disease significant co-expression genes." (PMID 36776884, 2023). "By correlating co-expressed genes as well as immune cell ratios, we obtained genes with significant correlation with immune cell ratios (SIRPA, AKR1A1, LEP, ALDOA) that will be validated in epilepsy data at the single cell level in an attempt to find immune genes that link heart and brain tissue." (PMID 36776884, 2023).
familial Alzheimer disease (1 paper, 2025). A degenerative disease of the brain that causes gradual loss of memory, judgment, and the ability to function socially. "Furthermore, integration with data from familial Alzheimer's disease indicated ALDOA, ENO1, PKM and PGAM1 are all upregulated in the early to middle stages of disease onset." (PMID 40491829, 2025).
Glycogen storage disease XII (1 paper, 2024). "ALDOA gene encodes fructose-1,6-bisphosphate aldolase A, and its mutations would cause Glycogen storage disease XII." (PMID 39039444, 2024).
Huntington disease (1 paper, 2022). Huntington disease (HD) is a rare neurodegenerative disorder of the central nervous system characterized by unwanted choreatic movements, behavioral and psychiatric disturbances and dementia. "Furthermore, Gene Set Enrichment Analysis supports that not only glycolysis and gluconeogenesis but also the kinetochore metaphase signaling pathway, Wnt//β-catenin signaling, sperm motility, and Huntington's disease signaling may play a role in regulating ALDOA and FBP1." (PMID 35404841, 2022).
Hypertension (1 paper, 2021). The presence of chronic increased pressure in the systemic arterial system. "The predictive values of ALDOA-Abs and FH-Abs for TIA were similar to that of hypertension, which is a typical risk factor of TIA." (PMID 34243715, 2021).
infertile (1 paper, 2021). "Antibodies against ENO1, ALDOA, GAPDH, and ODF1 were also detected in human semen from infertile men." (PMID 34576131, 2021).
invasive ductal carcinoma (1 paper, 2017). "Our present results showed that in a statistical average of 100 cases of invasive ductal carcinoma an increase of some key glycolytic enzymes occurred, namely: ALDOA, G3P KPYM, PGK1, and LDHA, while no relevant increase was observed for other glycolytic enzymes (i.e., ENOA, PGAM1, TPIS)." (PMID 28686225, 2017).
laminopathy (1 paper, 2023). A rare genetic disorder caused by mutations in genes encoding proteins of the nuclear lamina. "Our results are consistent with AldoA functioning in the nucleus and further suggest AldoA is relevant to the mechanisms of laminopathy and frailty." (PMID 37936983, 2023).
liver cirrhosis (1 paper, 2022). "For liver diseases, the high expression of ALDOA in patients with liver cirrhosis is closely related to the risk of liver cancer." (PMID 35804089, 2022).
meningioma (1 paper, 2025). A generally slow growing tumor attached to the dura mater. "For example, ALDOA, associated with the family Oxalobacteraceae, is expressed at higher levels in grade II meningiomas." (PMID 40873641, 2025).
meningoencephalitis (1 paper, 2022). Inflammation of the meninges and brain, generally secondary to an infectious cause. "In addition, our validation study found that ALDOA was higher in pigs naturally affected by meningoencephalitis caused by S. suis compared with healthy pigs." (PMID 35743177, 2022).
metastatic tumors (1 paper, 2025). "In metastatic tumors, pathway and TF analyses revealed strong hypoxia-inducible factor-1α–driven hypoxia activation, influencing glycolysis (SLC2A1, SLC2A3, PGK1, PDK1, PGM1, and ALDOA), angiogenesis (ANGPTL4 and ADM), and survival in low oxygen (BNIP3, BNIP3L, and NDRG1)." (PMID 40736012, 2025).
muscle disorders (1 paper, 2025). "Given vitamin D deficiency’s association with muscle disorders and ALDOA elevation, further exploration of SDR42E1-ALDOA interactions is warranted." (PMID 40756515, 2025).
non-alcoholic fatty liver disease (1 paper, 2021). "Interestingly, obese individuals with non-alcoholic fatty liver disease express increased levels of ALDOA and ENO compared to obese controls and enhanced expression of glycolysis-related genes is associated with tumor immune resistance." (PMID 34884992, 2021).
oral cancer (1 paper, 2024). "This study confirmed that the high expression of ALDOA is associated with chemotherapy resistance in oral cancer by bioinformatics methods." (PMID 39247585, 2024). "Under hypoxia, the high expression of ALDOA is associated with chemotherapy resistance in oral cancer." (PMID 39247585, 2024). "This indicates that the hypoxia gene ALDOA can be used as a predictor of the prognosis and chemotherapy efficacy of oral cancer." (PMID 39247585, 2024). "While previous studies have investigated the relationship between ALDOA and oral cancer 15, 16, primarily focusing on prognostic implications." (PMID 39247585, 2024). "Therefore, we determined that ALDOA was the core hypoxia gene of chemotherapy resistance in oral cancer." (PMID 39247585, 2024). "We identify hypoxia gene ALDOA as a core gene of chemoresistance in oral cancer." (PMID 39247585, 2024). "Hypoxia gene ALDOA may be a potential target for the treatment of oral cancer." (PMID 39247585, 2024).
pituitary tumor (1 paper, 2021). A benign or malignant neoplasm affecting the pituitary gland. "The expression of ALDOA has not yet been studied in pituitary tumors, which would be an interesting avenue for future research." (PMID 34869733, 2021).
Renal cyst (1 paper, 2024). A fluid filled sac in the kidney. "The observed substantial downregulation of ALDOB (−233×) and upregulation of ALDOA (1.7×) further support increased glycolytic flux in renal cysts." (PMID 39000280, 2024).
rhabdomyolysis (1 paper, 2014). Necrosis or disintegration of skeletal muscle often followed by myoglobinuria. "We identified a deleterious homozygous mutation in the ALDOA gene in 3 siblings with episodic rhabdomyolysis without hemolytic anemia." (PMID 25392908, 2014).
rheumatoid arthritis (1 paper, 2019). A chronic, systemic autoimmune disorder characterized by inflammation in the synovial membranes and articular surfaces. "The reactivity of anti-aldolase A autoantibody in the serum of patients with rheumatoid arthritis was evaluated using denatured and native AldoA, and this autoantibody predominantly bound to denature enzyme." (PMID 30858938, 2019).
small cell lung carcinoma (1 paper, 2024). Small cell lung cancer (SCLC) is a highly aggressive malignant neoplasm, accounting for 10-15% of lung cancer cases, characterized byrapid growth, and early metastasis. "MA treatment of small cell lung carcinoma DMS114 cells caused downregulation of glycolytic proteins (ALDOA, GAPDH, ENO1, PyKM2 and LDHA) as well as upregulation of OxPhos proteins (cytochrome b-c1 complex subunit 2 and cytochrome c oxidase subunit 5B)." (PMID 39288141, 2024).
stress cardiomyopathy (1 paper, 2023). "According to the previous results, in stress cardiomyopathy, the ALDOA gene is positively associated with NK cells but negatively associated with M2 macrophages." (PMID 36776884, 2023). "Meanwhile, high ALDOA expression in the heart is accompanied by a decrease in the proportion of M2 macrophages, leading to an inflammatory manifestation with extensive infiltration in the heart, which is consistent with clinical manifestations of stress cardiomyopathy are consistent." (PMID 36776884, 2023).
triple-negative breast carcinoma (1 paper, 2021). An invasive breast carcinoma which is negative for expression of estrogen receptor (ER), progesterone receptor (PR), and human epidermal growth factor receptor 2 (HER2). "Despite the fact that MDA-MB-231 cells are triple negative breast cancer cells and even the wild type cells are highly glycolytic, proteins critical to glycolysis, including ALDOA, ENO1 and G3P, were all significantly upregulated in the p300 KD cells." (PMID 34884992, 2021).
Uterine leiomyoma (1 paper, 2022). The presence of a leiomyoma of the uterus. "In uterine leiomyoma, SLC2A1 and ALDOA were identified as HIF-1α-responsive genes." (PMID 35404841, 2022).
tumor (123 papers, 2011 to 2026). "Spatial transcriptomic and immunofluorescence analyses confirmed the co-localization of ALDOA with CD68 + tumor-associated macrophages (TAMs)." (PMID 41239433, 2025). "ALDOA's expression in various cancers is closely linked to tumor invasiveness and metastatic potential." (PMID 40520908, 2025). "Spatial transcriptomics and immunofluorescence staining further confirm the co-localization of ALDOA with CD68+ tumor-associated macrophages, suggesting a direct role in macrophage-mediated immune modulation." (PMID 41239433, 2025). "Beyond its intrinsic role in tumor cells, ALDOA has also been linked to the tumor microenvironment, influencing immune cell infiltration and immune evasion." (PMID 41239433, 2025). "In lung adenocarcinoma, overexpression of ALDOA is linked to advanced tumour stages and unfavourable outcomes, suggesting its role as an independent prognostic factor." (PMID 41154605, 2025). "Our analysis also linked ALDOA expression to tumor mutational burden and microsatellite instability in several cancers." (PMID 41239433, 2025). "These in vivo results confirm that ALDOA deficiency dramatically suppresses HCC cell proliferation but has a limited impact on tumor infiltration and metastasis." (PMID 40708574, 2025). "Aldolase A (ALDOA), a key glycolytic enzyme, has been implicated in tumor progression and metabolic reprogramming across multiple cancers." (PMID 41239433, 2025). "Classified into three groups (ALDOA, ALDOB, and ALDOC), ALDOA has been implicated in promoting tumor growth and metastasis in various cancers." (PMID 39765841, 2024). "The orthotopic implantation tumor model also showed smaller HCC tumor models formed by LCSCs that underwent the ALDOA K230/322R mutation compared to the WT group." (PMID 39099416, 2024). "Next, the effect of ALDOA K230/322 mutation on the tumorigenic ability of LCSCs was detected by in vivo nude mice subcutaneous tumor formation assay." (PMID 39099416, 2024). "The results showed that the temperature of the tumor formation site in nude mice with the ALDOA K230/322R mutation was significantly lower than that of the WT group." (PMID 39099416, 2024). "The immunoprecipitation test results showed that the lactylation level of ALDOA in the orthotopic transplanted tumor formed by K230/322R mutation was significantly reduced, consistent with the results of cell experiments." (PMID 39099416, 2024). "To verify the changes in glycolysis ability of LCSCs in vivo after ALDOA K230/322R mutation, we used a thermal imager to detect the temperature at the tumor site in mice." (PMID 39099416, 2024). "The results showed that ALDOA deficiency significantly retarded tumor growth and reduced tumor volume and weight." (PMID 37431681, 2023). "The balance between full-length ALDOA and its spliced variants could ultimately dictate tumor cell fate in response to immune pressure." (PMID 41239433, 2025). "Translating these findings to GC, combinatorial strategies targeting ALDOA/ENO1 with immunotherapy may synergize by reversing macrophage-mediated immunosuppression, as ALDOA/ENO1 expression correlates with tumor-associated macrophage infiltration." (PMID 41049005, 2025). "Immune subtype analysis further revealed that ALDOA-high tumors were predominantly associated with the C1 (Wound Healing) subtype, indicating an angiogenesis and oncogenic proliferating role for ALDOA in certain tumor contexts." (PMID 41239433, 2025). "Furthermore, immunofluorescence (IF) staining demonstrated co-localization of ALDOA with CD68 + tumor-associated macrophages (TAMs), suggesting a possible link between ALDOA expression and the immunosuppressive tumor microenvironment." (PMID 41239433, 2025). "This suggests that ALDOA/ENO1 may influence the survival of GC patients by affecting the infiltration of tumor-associated macrophages (TAMs)." (PMID 41049005, 2025).
tumor (continued). "In this view, the underlined data suggest that ALDOA’s effect on various tumor tissues may be context-dependent, and the precise molecular pathways driving the discrepancy will require further investigation in the future." (PMID 39755705, 2025). "ALDOA is frequently upregulated in GC tissues compared to adjacent normal tissues in IHC studies, associated with enhanced glycolytic activity, contributing to tumour progression." (PMID 41154605, 2025). "The concept of generating iTSCs through the overexpression of ALDOA presents an intriguing paradox, considering that ALDOA, a glycolytic enzyme, exhibits heightened expression in diverse tumor types, often being linked to tumorigenesis and the advancement of the disease." (PMID 37896207, 2023). "In summary, ALDOA inhibits DNA repair but releases the cell cycle arrest induced by DNA damage, which allows cells to continue to expand and DNA damage to remain and accumulate, induces genic mutations and promotes the occurrence and development of tumours." (PMID 34565365, 2021). "We also verified that ALDOA was the direct target of miR-122, and the tumor suppressive effects caused by DIO3OS knockdown or miR-122 overexpression could be rescued by re-expression of ALDOA in PC cells." (PMID 31384177, 2019). "Notably, ALDOA expression was most strongly correlated with the M0 macrophage subset, implying that ALDOA may be involved in macrophage polarization and tumor-associated macrophage (TAM)-mediated immunosuppression." (PMID 41239433, 2025). "We demonstrate that PLBD1-AS1 promotes tumor cell proliferation, migration, and invasion by interacting with the glycolytic enzyme ALDOA and enhancing glycolytic flux." (PMID 41950246, 2026). "The powerful T-cell reinvigoration upon checkpoint blockade likely induces profound metabolic stress in tumor cells, triggering a compensatory upregulation of ALDOA and other glycolytic enzymes as a survival mechanism." (PMID 41239433, 2025). "Further validation using immunohistochemistry in patient-derived samples confirmed that ALDOA protein levels are significantly elevated in LUSC tumor tissues compared to normal adjacent tissues." (PMID 41239433, 2025). "Since the tumor-node-metastasis (TNM) stage closely correlates to tumor malignancy, we investigated the correlation between the expression level of ALDOA and different stages of TNM (i.e., stage I, II, III, and IV)." (PMID 39755705, 2025). "The stability of ALDOA is crucial for tumor cell proliferation and metabolism, and inhibiting ALDOA can reduce tumor growth." (PMID 40520908, 2025). "Given the growing importance of tumor metabolism and immune regulation in cancer therapy, ALDOA emerges as a critical link between metabolic adaptation and immune suppression, opening new avenues for targeted therapy in LUSC." (PMID 41239433, 2025). "According to the obtained results, the ALDOA mRNA level was found to be elevated in CRC tumor tissues and cancer cells, as compared to the normal tissues." (PMID 39755705, 2025). "Beyond prognosis, our data reveal ALDOA’s central role in driving tumor progression through metabolic reprogramming, macrophage-mediated immune suppression, and therapy resistance, positioning it as a multi-faceted therapeutic node." (PMID 41239433, 2025). "Using multiple immune deconvolution algorithms and single-cell RNA sequencing analysis, we demonstrated that ALDOA is highly expressed in both malignant tumor cells and monocyte-derived macrophages within the tumor microenvironment." (PMID 41239433, 2025). "Prognostic genes including EZH2, PCNA, and BIRC5 were specifically expressed in epithelial clusters, while CHMP4C, ATP13A2, and ALDOA showed broader expression patterns, supporting their tumor-specific roles." (PMID 40678068, 2025). "Comparative proteomic analysis revealed a significant upregulation of ALDOA in tumor tissues compared to adjacent normal counterparts." (PMID 41239433, 2025).